HLA-DPB1 (major histocompatibility complex, class II, DP beta 1)
Diseases named in the same sentence as HLA-DPB1 in open-access papers (continued):
Sharing a sentence is not in itself a finding about the gene and the disease.
leukemia (11 papers, 2008 to 2024). A malignant (clonal) hematologic disorder, involving hematopoietic stem cells and characterized by the presence of primitive or atypical myeloid or lymphoid cells in the bone marrow and the blood. "In previous studies, certain HLA-DPB1 mismatch constellations were shown to be beneficial in terms of lower risk of leukemia relapse after alloHSCT." (PMID 32443793, 2020). "HLA-DPB1 antigens are mismatched in about 80% of allogeneic hematopoietic stem cell transplantations from HLA 10/10 matched unrelated donors and were shown to be associated with a decreased risk of leukemia relapse." (PMID 32443793, 2020). "Therefore, HLA-DPB1 mismatches predict a significantly lower risk of leukemia relapse." (PMID 35356211, 2022). "In fact, both TCR-transduced CD4+ T cells effectively lysed WT1332 peptide-pulsed B-LCL and WT1-expressing HLA-DPB1*05:01-positive leukemia cell line, C2F8-CIITA." (PMID 36939853, 2023). "The use of HLA-DPB1 in unrelated donor hematopoietic stem cell transplantation has been shown to improve outcomes in patients with leukemia relapse." (PMID 35356211, 2022). "More recently, HLA-DPB1 was found to be downregulated on leukemia blasts in a significant fraction of patients who have relapsed after transplantation, implicating an important role of HLA-DPB1 as a target antigen for GvL reactivity but also its potential involvement in immune escape after alloHSCT." (PMID 32443793, 2020). "In conclusion, T cells engineered with selected allo-HLA-DPB1 specific TCRs might be powerful off-the-shelf reagents in allogeneic T-cell therapy of leukemia." (PMID 32443793, 2020). "HLA-DPB1 locus mismatches significantly protect against leukemia relapse." (PMID 28206973, 2017). "As part of the UKCCS, we obtained HLA-DPB1 types for 982 cases of childhood leukaemia." (PMID 18334973, 2008). "However, in specific cases, HLA-DPB1 mismatching could be beneficial for the graft-versus-leukemia effect." (PMID 28018351, 2016). "Importantly, as an extension beyond previous studies of HLA-DPB1 and childhood leukemia, the California study also examined interactions between proxies for delayed infections in childhood (daycare attendance, ear infections, and breastfeeding) with the observed DP1 association." (PMID 24377085, 2013). "On the other hand, they lysed neither WT1332 peptide-non-pulsed B-LCL nor HLA-DPB1*05:01-negative WT1-expressing leukemia cell line, K562." (PMID 36939853, 2023). "HLA-DPB1 locus nonpermissive mismatches have a significantly protective effect against leukemia relapse, simultaneously have no significantly increased risk of TRM, mortality or DFS." (PMID 28206973, 2017). "HLA-DPB1 locus mismatches had a significantly protective effect against leukemia relapse, which was attributed to nonpermissive HLA-DPB1 mismatches." (PMID 28206973, 2017). "Indeed, HLA-DPB1 mismatches are associated with increased risks of acute GvHD after 8 of 8 HLA-matched MUD HCT, but also with a significantly reduced risk of leukemia relapse, resulting in no net impact on overall survival (OS)." (PMID 39512351, 2024).
cervical cancer (10 papers, 2013 to 2024). A primary or metastatic malignant neoplasm involving the cervix. "The combined action of folate biosynthesis and graft-vs.-host disease was demonstrated to be significantly associated with cervical cancer in suit: HLA-DPB1." (PMID 34149809, 2021). "The HLA-DPB1*02:02 and *13:01 alleles confer a risk of cervical cancer but DPB1*05:01 allele renders protection against the disease." (PMID 30333560, 2018). "Genetic associations have been observed with HLA-DPB1 gene in cervical cancer in Chinese and Taiwanese populations using case-control study." (PMID 30333560, 2018). "SNP rs4282438, located in the HLA-DPB1/2 region, has been proven to be a cervical cancer association variant in both Chinese and Taiwanese populations." (PMID 30333560, 2018). "For instance, the HLA-DP gene polymorphisms (HLA-DPB1*03:01 and HLA-DPB1*13:01) have been significantly associated with an increased risk of cervical cancer in Chinese populations." (PMID 38929796, 2024). "Based on these studies, many alleles like HLA-DPB1∗02:02, DPB1∗03:01, DPB1∗04:02, DPB1∗05:01, DPB1∗13:01, rs9277535 (DPB1), rs4282438 (DPB2), rs3117027 (DPB2), and rs3077 (DPA1) were reported to be significantly associated with cervical cancer." (PMID 30009173, 2018). "HLA-DP gene polymorphisms (HLA-DPB1⁎03:01, DPB1⁎04:02, DPB1⁎13:01, rs9277535, and rs3117027) were significantly associated with cervical cancer." (PMID 30009173, 2018). "Susceptibility to HPV infection or cervical cancer and precancerous lesion development was associated with the HLA class II: HLA-DRB1 alleles; HLA-DQB1 alleles; HLA-DPB1 alleles; and classes I and II haplotypes." (PMID 23936772, 2013). "In a Phase I study involving HLA-DPB1*0401-restricted T-cell receptors (TCRs) that was designed to specifically recognise MAGE-A3 antigen, complete remission was seen in a patient with metastatic cervical cancer, and partial remission was seen in 3 patients." (PMID 34359776, 2021).
melanoma (10 papers, 2014 to 2025). A malignant, usually aggressive tumor composed of atypical, neoplastic melanocytes. "Of such linked HLAs, overlap between melanoma and CI-associated BP adverse events only includes HLA-DPB1* 01 and HLADPB1*10 which were found in patients A and I who had CI-associated BP adverse events and melanoma." (PMID 38259857, 2023). "HLA-DPB1, critical for presenting extracellular peptides, shows reduced expression in melanoma patients resistant to immune checkpoint therapy, indicating its relevance as a prognostic marker." (PMID 39355255, 2024). "By LASSO Cox regression analysis, we constructed a prognosis model based on 5-mRNA (SRGN, IDO1, RARRES3, CCL4, HLA-DPB1), which has great predictive value for the overall survival of melanoma." (PMID 34805163, 2021). "In addition, MAGE-A3-specific TCRs in the context of HLA-DPB1*04:01 were isolated and identified from a regulatory T-cell clone (6F9), which was generated from the peripheral blood of 2 melanoma patients after MAGE-A3 vaccination." (PMID 37649599, 2023). "The ITRGM signature includes GBP5, HLA-DPB1, XBP1, CD40, CXCL10, and TNFSF13B, each playing pivotal roles in the immune response and tumor microenvironment of melanoma." (PMID 39355255, 2024). "Moreover, CD163+/CD11c+ DCs within CRATERs presented a statistically significant increase in HLA-A and HLA-DPB1 levels, corresponding to MHC class II, and MART-1 melanoma antigen, compared with elsewhere in the tumor." (PMID 41109214, 2025). "Other research found that class II molecules (HLA-DPA1, HLA-DPB1, HLA-DQA1, HLA-DRA, HLA-DRB1, HLA-DRB5) are important biomarkers in the occurrence and progression of melanoma tumors, and their expression levels are closely related to prognosis and immune infiltration." (PMID 39969704, 2025).
chronic hepatitis B (9 papers, 2011 to 2024). "HLA-DPA1*01:03 and HLA-DPB1*13:01 were previously shown to be significantly associated with chronic hepatitis B in the Thai population with protective and susceptibility effects, respectively." (PMID 35769989, 2022). "In addition, our previous GWAS confirmed and identified the association of SNP markers located on HLA-DPA1 (rs3077) and HLA-DPB1 (rs9277535) genes with susceptibility to chronic hepatitis B (CHB) and HBV clearance in Japanese and Korean subjects." (PMID 24520320, 2014). "We also found that the HLA-DPA1 and HLA-DPB1 genes were significantly associated with protective effects against chronic hepatitis B (CHB) in Japanese, Korean and other Asian populations, including Chinese and Thai individuals (Pmeta = 4.40×10−19 for rs3077 and Pmeta = 1.28×10−15 for rs9277542)." (PMID 22737229, 2012). "Hence, we could confirm that the polymorphisms of HLA-DPA1 and HLA-DPB1 gene play a very important role in chronic hepatitis B virus infection in southern and northern Han Chinese populations." (PMID 21904616, 2011). "In 2009, significant associations between chronic hepatitis B (CHB) and a region including HLA-DPA1 and HLA-DPB1 were identified using 786 Japanese individuals having CHB and 2,201 control individuals through a two-stage genome-wide association study (GWAS)." (PMID 22737229, 2012).
Sepsis (9 papers, 2020 to 2024). Sepsis is defined as life-threatening organ dysfunction caused by a dysregulated host response to infection. "Our finding identified miR-let-7b-5p in FFL modulation, which associates SPIB and HLA-DPB1 in sepsis." (PMID 35831411, 2022). "Sepsis-linked decrease transcription of the classical HLA gene such as HLA-DPB1 and its interplay with miR-let-7b-5p and transcription factor SPIB was observed." (PMID 35831411, 2022). "The “Sepsis Metascore” subpanel on another hand, consists of a sepsis-specific transcripts including CEACAM1, C3AR1, GNA15, and HLA-DPB1 which have previously been linked to sepsis." (PMID 35186993, 2022). "Another interaction between HLA-DPB1, which, according to our systematic review is involved in neurodegeneration, and miR-let-7b-5p, which is known to prevent AD progression, was previously identified in other studies focusing on inflammation in sepsis." (PMID 39126112, 2024). "Gene expression analysis revealed a sepsis-associated decreased transcription of (i) the classical HLA genes HLA-DRA, HLA-DRB1, HLA-DPA1 and HLA-DPB1 and (ii) the gene of the MHC-II master regulator, CIITA (Class II Major Histocompatibility Complex Transactivator)." (PMID 33939725, 2021). "Even more importantly, the observed reduction in classical HLA-DRA, HLA-DRB1, HLA-DPA1 and HLA-DPB1 transcription as well as the decline in monocyte HLA-DR surface expression persisted in all patients with postoperative sepsis despite a recovery of CIITA transcription levels during the study period." (PMID 33939725, 2021). "Additional experiments revealed that the observed elevation in CTCF expression, CTCF binding at CM1, CM2, CM3 and CM9 as well as the reduced expression of adjacent classical HLA genes HLA-DRA, HLA-DRB1, HLA-DPA1 and HLA-DPB1 persisted in all patients with postoperative sepsis." (PMID 33939725, 2021).
viral infection (9 papers, 2020 to 2025). "Among the 6 genes, over-expressed genes (HK3, DEFA4, BATF) were positively correlated with severity of viral infection, and under-expressed genes (HLA-DPB1, LY86, TGFBI) were negatively correlated with severity." (PMID 35042868, 2022). "Down-regulation of HLA-DPB1 in B-2 cells suggested a decreased ability of antigen presentation in response to viral infection." (PMID 34895340, 2021). "FDR analysis using all p-values obtained a minimum q-value of 27% for the associations with the four lowest p-values, namely HLA-DQB1 with sepsis infection, HLA-DQA1 with other infections, HLA-DPB1 with CNS infection and HLA-DQB1 and viral infection." (PMID 34059071, 2021). "Each of the 6 genes were significantly differentially expressed between patients with viral infections who survived and those who did not, of which 3 genes (DEFA4, BATF, HK3) were higher and 3 genes (TGFBI, LY86, HLA-DPB1) were lower in those who died." (PMID 35042868, 2022).
systemic sclerosis (8 papers, 2011 to 2024). A chronic disorder, possibly autoimmune, marked by excessive production of collagen which results in hardening and thickening of body tissues. "Previous studies reported the association of HLA-DPB1 with the spontaneous clearance of hepatitis B virus (HBV) in Japanese and American populations, and susceptibility to systemic sclerosis (SSc) in Korean and North American populations." (PMID 33308178, 2020).
diabetes (6 papers, 2013 to 2022). "Previous studies have shown that HLA-DPB1 is associated with diabetes and dilated cardiomyopathy, therefore deeper investigation of HLA-DPB1 in diabetic heart failure is required." (PMID 32602534, 2020). "Moreover, the HLA subtypes HLA-A*11:01, HLA-B*46:01, HLA-DPA1*01:03, and HLA-DPB1*05:01 were found to be associated with heart disease, stroke, diabetes, and hypertension among subjects with GD." (PMID 35321340, 2022). "Since these are mainly early-onset strokes, the same study showed that higher blood pressure levels were found in subjects with polymorphisms of these genes, while the polymorphisms of other genes, CSN3, HLA-DPB1 and SH3TC1, are associated with cardiovascular diseases and diabetes mellitus." (PMID 35741740, 2022).
multiple sclerosis (6 papers, 2010 to 2023). A progressive autoimmune disorder affecting the central nervous system resulting in demyelination. "It has been shown that change in the methylation of HLA DPB1 (Major Histocompatibility Complex, class II, DP Beta 1) contributes to the development of multiple sclerosis, a disease of the central nervous system." (PMID 37175405, 2023).
sarcoidosis (6 papers, 2016 to 2024). Sarcoidosis is a multisystemic disorder of unknown cause characterized by the formation of immune granulomas in involved organs. "The ACCESS project (A Case Control Etiologic Study of Sarcoidosis) was the first to show that HLA-DRB1 (*1101) and HLA-DPB1 (*0101) alleles contributed significantly to the risk of sarcoidosis, in both black and white populations." (PMID 32823753, 2020). "After correction for multiple comparisons, variants HLA-DPB1*02:01 (pcorr = 5.92 × 10−07), HLA-DPB1*02:02 (pcorr = 0.017), HLA-DPB1*04:01 (pcorr = 1.94 × 10−05), and HLA-DPB1*13:01 (pcorr = 0.027) were found protective for sarcoidosis." (PMID 35661780, 2022). "Variants previously associated with sarcoidosis risk (HLA-C*03:04, HLA-DRB1*12:01, HLA-DRB1*14:54) and a known protective variant HLA-DPB1*04:01, were associated with sarcoidosis in Koreans." (PMID 35661780, 2022). "Similar to most immune-mediated diseases, disease susceptibility in CBD and sarcoidosis is driven by the expression of certain MHCII molecules, primarily HLA-DPB1 in CBD and several HLA-DRB1 alleles in sarcoidosis." (PMID 32256501, 2020). "Certain MHCII molecules, primarily HLA-DPB1 in CBD and several HLA-DRB1 alleles in sarcoidosis, increase disease susceptibility." (PMID 32256501, 2020). "In addition to HLA-DPB1*04:01, we characterized variants HLA-DPB1*02:01 and HLA-DPB1*02:02 as protective factors in Korean sarcoidosis patients." (PMID 35661780, 2022). "Even in this highly environmental inducing context, it was recently shown that more that seventeen novel HLA alleles were associated with an increased risk of sarcoidosis in exposed individuals, with OR values varying from 1.66 (HLA-DPA1/HLA-DPB1) to 5.21 (HLA-DRB1)." (PMID 32823753, 2020). "Lastly, HLA-DPB1 with a glutamic acid at amino acid position 69 (Glu69) (or HLA-DPB1*02:01) allele confers an increased risk of beryllium sensitization and characterized CBD as a separate entity from sarcoidosis, which can be named a metal-induced granulomatous disorder." (PMID 32823753, 2020). "Finally, regarding the HLA-DPB1 locus, in our Korean cohort, HLA-DPB1*02:02 could be associated with a better sarcoidosis prognosis, as it did not occur in patients with CXR stage 2–4." (PMID 35661780, 2022).
Stroke (6 papers, 2009 to 2024). Sudden impairment of blood flow to a part of the brain due to occlusion or rupture of an artery to the brain. "In contrast, some polymorphisms in TNFα, β-adrenergic receptor 2 (ADRB2) and HLA-DPB1*1701 were protective against stroke." (PMID 23762099, 2013). "In the small vessel stroke group, HLA DPB1*0401 was associated with increased stroke risk, whereas DPB1*1701 conferred protection from stroke." (PMID 20401335, 2009). "The exomic analyses informed upon by our lacunar stroke GWAS results identified two genes, CSN3 and HLA-DPB1, which appeared to have excess variation in our stroke cases." (PMID 22536414, 2012).
lung cancer (5 papers, 2019 to 2024). A malignant neoplasm involving the lung. "In gene polymorphism research, HLA-DPB1 mutations have been regarded as signatures associated with gastric and lung cancers." (PMID 33511023, 2021).
psoriasis (5 papers, 2019 to 2026). An autoimmune condition characterized by red, well-delineated plaques with silvery scales that are usually on the extensor surfaces and scalp. "DPB1-F35L was in strong linkage disequilibrium with a previously reported psoriasis-associated allele, HLA-DPB1∗05:01 (r2 = 0.76)." (PMID 33134369, 2020).
rubella (5 papers, 2010 to 2021). A viral infection caused by the rubella virus. "Our studies identified a SNP (rs2064479, p = 8.6 × 10−8) in the class II HLA-DPB1 gene region associated with variations in rubella-specific Ab titers after rubella vaccine." (PMID 32670279, 2020). "Of interest, the association of the HLA-DPB1*0301 allele with the poor response to the rubella vaccine was replicated in a recent GWAS that investigated around five million variants in 1000 healthy individuals vaccinated with the MMR vaccine." (PMID 33167413, 2020). "At the level of HLA alleles, HLA-DQB1*03:01 showed the lowest P value for association with EBV EBNA (P = 1.3 × 10−7), and HLA-DPB1*03:01 was the top signal for rubella (P = 3.8 × 10−6)." (PMID 30053915, 2018).
type 1 diabetes (5 papers, 2013 to 2024). "In type I diabetes mellitus, HLA-A, HLA-B, HLA-C, HLA-DPB1 and GAD1 exhibited significantly different expression levels." (PMID 26062681, 2015).
Autoimmunity (4 papers, 2021 to 2024). The occurrence of an immune reaction against the organism's own cells or tissues. "Therefore, we hypothesized that the HLA-DPB1 polymorphism (rs1126504) is important for the development of autoantibodies in autoimmune FXIII deficiency." (PMID 34506591, 2021).
chronic beryllium disease (4 papers, 2012 to 2023). Chronic beryllium disease (CBD) is a granulomatous, interstitial lung disease that occurs in individuals who develop beryllium sensitization (BeS), a cell-mediated immune response to environmental and occupational beryllium exposure. "Thus, HLA-DPB1 testing has no role as a diagnostic investigation for chronic beryllium disease." (PMID 37250639, 2023).
gastric cancer (4 papers, 2020 to 2025). A primary or metastatic malignant neoplasm involving the stomach. "We found that 2 genes, HLA-DRA (Betasmr = -0.33) and HLA-DPB1 (Betasmr = -0.18), were negatively associated with gastric cancer." (PMID 38877387, 2024). "The mechanism of HLA-DPB1 in gastric cancer remains to be further explored." (PMID 38877387, 2024). "Moreover, In our study, we found a negative association between HLA-DPB1 and gastric cancer." (PMID 38877387, 2024). "For example, the M1 Macrophage marker NOS2 and the dendritic cell marker, HLA-DPB1 and CD1C, were significantly correlated with ARHGAP11A expression in gastric cancer." (PMID 34733886, 2021).
graft versus host disease (4 papers, 2014 to 2024). An immune system disorder that occurs after allogeneic hematopoietic stem cell transplant and is a reaction of donor immune cells against host tissues. "rs9277534 has been linked to hepatitis B virus recovery/persistence and the risk of graft-versus-host disease with HLA-DPB1 mismatching transplantation of hematopoietic cells, but its role along with that of HLA-DP expression in AIH have not been fully clarified." (PMID 30093645, 2018).
hepatocellular carcinoma (4 papers, 2015 to 2025). A malignant tumor that arises from hepatocytes. "Lastly, HLA-DPB1*05:01:01 was identified as a potential risk HLA allele for development of hepatocellular carcinoma (HCC) in PBC patients." (PMID 37325616, 2023).